LINC00924 (long independently transcribed non-coding RNA 924)
Gene: Long non-coding RNA gene on chromosome 15 (95,296,424 to 95,615,635, forward strand). Ensembl gene ENSG00000259134.
Diseases named in the same sentence as LINC00924 in open-access papers:
LINC00924 is named in the same sentence as 4 diseases in open-access papers, as found by Europe PMC text mining. Sharing a sentence is not in itself a finding about the gene and the disease. The quoted sentences say what the papers report.
gastric cancer (1 paper, 2022). A primary or metastatic malignant neoplasm involving the stomach. "In this article, we further proved that LINC00924 could play an oncogenic role in gastric cancer." (PMID 36418856, 2022).
hepatocellular carcinoma (1 paper, 2022). A malignant tumor that arises from hepatocytes. "However, a recent publication suggested that LINC00924 functioned as tumor suppressor via sponging miR-6755–5p in hepatitis B virus-related hepatocellular carcinoma." (PMID 36418856, 2022).
tumor (3 papers, 2022 to 2024). "RT–qPCR results showed that LINC00924, LINC00944, and LINC00865 were highly expressed in tumour tissues, while LINC00702 and ZFAS1 were expressed at low levels in tumour tissues." (PMID 36936957, 2023).
cancer (1 paper, 2022). A tumor composed of atypical neoplastic, often pleomorphic cells that invade other tissues. "Previous studies showed that hnRNPC could regulate cancer-specific alternative cleavage, which suggested that LINC00924 might regulate premRNA splicing via hnRNPC." (PMID 36418856, 2022). "Finally, it remains unclear whether LINC00924-induced lipid metabolic reprogramming is GC-specific or it also present in other types of cancer; more studies are needed to clarify this issue." (PMID 36418856, 2022).